CD1D (CD1d molecule)
Diseases named in the same sentence as CD1D in open-access papers (continued):
Sharing a sentence is not in itself a finding about the gene and the disease.
myeloma (continued). "Moreover, in vitro experiments showed that CD1d ligation can cooperate with other anti-myeloma agents to induce cell death, raising the possibility of incorporating αCD1d antibody treatment to the arsenal of therapies targeting early-stage myeloma." (PMID 38579449, 2024). "In this regard, to target CD1d+ MM cells, CD19-CAR-NKT cell has been developed with the capability of targeting both CD1d and CD19 antigens on myeloma cells." (PMID 33781320, 2021). "Myeloma cells express CD1d and are sensitive to lysis by NKT cells, but CD1d expression is downregulated during the progression of the disease and eventually lost altogether." (PMID 29967611, 2018). "Some cancer types also express CD1d, including prostate, glioma, hepatocellular carcinoma, B-CLL, and multiple myeloma, suggesting NKT cells can directly interact with tumors." (PMID 24212972, 2011). "In trial NCT04754100, donor-derived, pure, unedited iNKT cell products, manufactured and cryopreserved ahead of demand, were administered to unrelated and non-lymphodepleted patients with relapsed/refractory multiple myeloma, known to express CD1d." (PMID 41000376, 2025). "The evidence is somewhat thinner in the context of hematologic malignancies, however, CD1d has been shown to be expressed on multiple myeloma cells, as well as AML cells and iNKT exhibited reactivity to CD1d positive tumor cells in vitro in a α-GalCer–dependent manner." (PMID 33680931, 2020). "Engagement of CD1d by anti-CD1d monoclonal antibodies was able to induce myeloma cell death in vitro which was not induced by caspase-activation but was rather associated with overexpression of the pro-apoptotic protein Bax and mitochondrial membrane potential loss." (PMID 26895468, 2016). "A lyso-derivative of the central nervous system lipid sulfatide was found to be recognized by a CD1d-restricted murine T cell line, and lyso-phosphatidylcholine (LPC) was reported to be recognized by CD1d-restricted T cells that are expanded in the blood of human multiple myeloma patients." (PMID 19415116, 2009). "However, the LPC-reactive T cells from multiple myeloma patients did not utilize the characteristic T cell receptor of NKT cells and demonstrated skewed cytokine production, suggesting that they comprise a distinct CD1d-restricted T cell population." (PMID 19859526, 2009).
Obesity (25 papers, 2011 to 2025). Accumulation of substantial excess body fat. "To further investigate mechanisms underlying peripheral blood iNKT cells activation in obesity, we assessed CD1d expression on peripheral blood APCs." (PMID 41000378, 2025). "A plethora of studies have been conducted which associate the CD1d-NKT signalling axis with diet-induced obesity resulting in either disease protection or progression described for CD1d-deficient vs. WT mice." (PMID 38579449, 2024). "NKT cells control obesity-associated AT inflammation by interacting with CD1d-expressing cells such as adipocytes, Mφs, and DCs." (PMID 38426085, 2024). "By contrast, many other research groups suggested a pathogenic role of iNKT cells in obesity by showing an ameliorated metabolic phenotype in HFD-induced obese Traj18−/− or Cd1d−/− mice." (PMID 29963043, 2018). "α-GalCerBf stimulates iNKT cells in the context of CD1d, suggesting that alterations in the abundance of B. fragilis caused by obesity can affect NKT cell homeostasis." (PMID 29942311, 2018). "The ameliorated levels were almost equivalent to those seen in obese Cd1d1−/− mice, indicating that iNKT cells play a pathogenic role in diet-induced obesity and that the impact of CD1d deficiency on metabolism is iNKT cell dependent." (PMID 29963043, 2018). "In conclusion, we showed that deficiency of CD1d-resricted NKT cells suppressed the development of obesity, likely because inflammation of adipose tissue and liver were ameliorated and reduced levels of insulin resistance were induced." (PMID 22383967, 2012). "Although the NKT cell-Mφ interaction seems beneficial in obesity, CD1d-deficient Mφs may exhibit pro-inflammatory functions independent of their lack of cellular interaction with iNKT cells." (PMID 38426085, 2024). "To address whether alterations in liver CD1d expression and/or iNKTs reflected a cause or consequence of metabolic changes during obesity, we examined the physiology of lean, chow-fed CD1d−/− and controls." (PMID 21980475, 2011). "While no change in CD1d expression was detected on DCs or B cells, a downregulation was observed on CM, whereas IM and NCM showed increased CD1d expression in individuals with obesity." (PMID 41000378, 2025). "Direct effects of obesity-related factors (e.g., cytokines, glucose and free fatty acids (FFAs)) or indirect effects via altered self-lipid antigen presentation by CD1d-expressing APCs are both plausible." (PMID 41000378, 2025). "Accordingly, previous studies also revealed an increase in CD1d expression on visceral adipocytes from patients with obesity." (PMID 41000378, 2025). "They employed LysMCre-Cd1d1f/f mice as M2-specific CD1d-deleted mice, induced inflammation and insulin resistance during obesity due to the inhibition of M2-Mφ and iNKT cell interactions." (PMID 38426085, 2024). "The role of CD1d in the regulation of lipid metabolism described here, can have broad implications for metabolic diseases including obesity or atherosclerosis." (PMID 36344546, 2022). "iNKT activation by M1 macrophages exacerbated metaflammation and activation by M2-macrophage-ameliorated disease; M2-specific CD1d downregulation during obesity progression." (PMID 35163561, 2022). "Since β2m KO mice also lack CD8+ T cells, the role of NKT cells in obesity has been examined using CD1d KO mice fed an HFD." (PMID 29942311, 2018). "It has been shown that CD1d expression and glycolipid-reactive, CD1d-restricted NKT cells exacerbate the development of obesity and insulin resistance in mice." (PMID 27329323, 2016). "Several research groups have investigated the role of the CD1d-NKT cell axis in the development of diet-induced obesity (DIO) in mice." (PMID 27329323, 2016). "The present studies add to the developing knowledge of a role for NKT cells in obesity by showing that CD1d−/− mice, which lack both Type I and Type II NKT cells, are more susceptible to diet-induced obesity and metabolic perturbations." (PMID 24465369, 2014).
Obesity (continued). "These antigens could already be present in the serum of lean individuals but may be more abundantly loaded onto monocytes CD1d in individuals with obesity, thereby promoting iNKT cells activation." (PMID 41000378, 2025). "Since circulating Ox-LDL levels are increased in obesity, they may represent a relevant source of CD1d regulation in this context." (PMID 41000378, 2025). "Altogether, these data suggest that increased CD1d expression may enhance the presentation of endogenous lipid antigens, thereby contributing to iNKT cell activation in the context of obesity." (PMID 41000378, 2025). "Although IM and NCM are much less abundant than CM, their markedly longer lifespan in the bloodstream, their functional characteristics, together with CD1d upregulation, could promote their interactions with peripheral blood iNKT cells in obesity." (PMID 41000378, 2025). "This implies that NKT cells in HFD-fed mice are activated by unknown endogenous ligands presented by CD1d+ APCs, including flora-derived ligands, presumably even during obesity." (PMID 38426085, 2024). "While the role of CD1d/NKT cells in obesity and metabolic disorders remains unclear, some studies have found that CD1d-KO mice fed a high-fat diet have increased steatosis and impaired hepatic glucose tolerance." (PMID 36344546, 2022). "Given that a unique network of lipid metabolites is generated under metabolic stress in AT, CD1d-mediated lipid presentation may regulate a unique corresponding iNKT cytokine profile during obesity." (PMID 31379820, 2019). "Further, lipid excess also causes obesity-induced insulin resistance and hepatic steatosis in an NKT dependent manner and can be reversed by deficiency of either type I NKT cells or CD1d Another study reported a role of type II NKT cells in HFD induced obesity in mice." (PMID 31620124, 2019). "Notably, selective CD1d depletion on adipocytes appeared to suppress the development of obesity prior to macrophage polarization." (PMID 27329323, 2016). "We have shown in the present study that selective disruption of CD1d in adipocytes could reproduce these findings, suggesting that adipocytes are the most critical cell type expressing CD1d for the observed effects on obesity and inflammation." (PMID 27329323, 2016). "However, the relevant CD1d-expressing cells that influence the effects of NKT cells on the progression of obesity remain incompletely defined." (PMID 27329323, 2016). "To examine the effect on glucose homeostasis and hepatic lipid metabolism in another model of steatosis, independent of obesity, we examined CD1d−/− and WT mice fed a choline-deficient diet." (PMID 21980475, 2011). "Thus, we believe that iNKTs play a minimal if any role in metabolism in the context of diet-induced obesity, while CD1d plays a small but potentially important role in obesity." (PMID 21980475, 2011). "In addition to modulate CD1d expression on peripheral blood monocytes, obesity could also impact the composition and/or levels of these lipid antigens in tissues and serum, contributing to peripheral iNKT cell activation." (PMID 41000378, 2025). "Indeed, CD1d expression is commonly studied in adipose tissue in the context of obesity." (PMID 41000378, 2025). "Given the capacity of CD1d to modulate lipid metabolism and inflammatory responses, it is likely that its cell-intrinsic functions could play a role in the progression of metabolic diseases including obesity." (PMID 38579449, 2024). "In obesity, a reduced iNKT cell frequency was observed in both blood and VAT, and in the latter, it parallels a decreased CD1d-expressing cell number." (PMID 30455701, 2018). "We found that adipocyte-specific CD1d deletion abrogated NKT cell activation via adipocytes and thus ameliorated inflammation in adipose tissue, resulting in reduced obesity and improved insulin sensitivity." (PMID 27329323, 2016).
Obesity (continued). "Thus, IFN-γ produced by NKT cells is a critical regulator for the development of obesity, and its production by iNKT cells, vNKT cells and downstream effector or amplifier cells, NK cells, is controlled through antigen presentation by adipocytes that express CD1d." (PMID 27329323, 2016). "In the present study, we demonstrated that an innate lymphocyte of the T cell lineage, the CD1d-restricted NKT cell, also has an active role in the development of obesity." (PMID 22383967, 2012). "However, CD1d expression was upregulated on both IM and NCM subsets and downregulated on CM in individuals with obesity." (PMID 41000378, 2025). "Our results highlighted a significant upregulation of CD1d on both intermediate and non-classical monocyte subsets in individuals with obesity, which was also reversed after bariatric surgery-induced weight loss." (PMID 41000378, 2025). "Here, we summarize the correlation between the CD1d/NKT cell axis and obesity with a focus on AT inflammation and discuss factors that may contribute to the discrepancies among reports considering recent progress." (PMID 29942311, 2018). "Third, is the possibility that the absence of CD1d in intestinal cells influences the intestinal microbiome, which in turn, modifies the obesity phenotype." (PMID 29419749, 2018). "In addition to the new findings with Traj18−/− (1-1 L) mice, we observed similar weight gain curves for Traj18−/− (1-1 L) and Cd1d−/− mice on HFD, which would be consistent with a limited role of type 2 NKT cells in the development of obesity." (PMID 28986544, 2017). "Interestingly, CD1d is upregulated on intermediate and non-classical monocytes from individuals with obesity and its expression on both monocyte subsets is correlated with iNKT cell dysfunction." (PMID 41000378, 2025). "CD1d expression (MFI) was similar across APC types in individuals with or without obesity." (PMID 41000378, 2025). "Based on these preliminary results, we support the hypothesis of an impact of obesity on the presentation of CD1d-loaded lipid antigens by APCs rather than a direct effect on iNKT cells, even if this possibility cannot be excluded." (PMID 41000378, 2025). "Lipid metabolites from adipocytes that have been stressed by excess fatty acid accumulation in obesity may provide CD1-presented antigens that activate iNKT cells to decrease AT inflammation, based on evidence that adipose CD1d deletion prevented the anti-inflammatory effect of iNKTs." (PMID 31379820, 2019). "The response to CPAP therapy of CD1D and RAB20 suggests that the expression changes identified for these genes are due to OSA and not obesity." (PMID 32512511, 2020).
leukemia (24 papers, 2010 to 2026). A malignant (clonal) hematologic disorder, involving hematopoietic stem cells and characterized by the presence of primitive or atypical myeloid or lymphoid cells in the bone marrow and the blood. "Unexpectedly, before leukemia onset, all three transgenic CD1d-deficient mouse strains had fewer splenic transitional B cells than their CD1d-proficient counterparts." (PMID 26537916, 2015). "Interestingly, a high expression of CD1d has been associated with a poor prognosis in leukemia, but it should be noted that Vδ3 cells can expand and respond against CD1d+ target cells through a CD1d-restricted reactivity and with a potent secretion of effector molecules, such as IFN-γ." (PMID 34630403, 2021). "As CB-8F4CAR-iNK T cells are predominantly CD4+, we carefully evaluated their cytolytic activity against PR1/HLA-A2+ or αGalCer/CD1d+ leukemia and compared those with AD-8F4CAR-iNK T cells derived from multiple donors." (PMID 40519924, 2025). "Then, upon further old aging, approximately half of the ATAμκ Tg mice strongly increased B1 B cells in PBL and developed leukemia/lymphoma in spl and mLN under CD1d reduction." (PMID 36050343, 2022). "Accordingly, we showed that DLI-iNKTs produce proinflammatory cytokines as well as perforin exerting potent anti-leukemia cytotoxicity that is dependent on the expression of CD1d on leukemia cells." (PMID 31354710, 2019). "We conclude that DLI-iNKTs release cytotoxic effector molecules in a CD1d-dependent manner resulting in leukemia cell death." (PMID 31354710, 2019). "Here, CD1d expression on tumor cells was higher in patients with unfavorable prognosis, and the level of CD1d on leukemia cells was inversely correlated with iNKT-cell frequencies." (PMID 29375569, 2017). "CD8α+ and DN iNKT cells most frequently expressed CD56, CD161 and NKG2D and most potently killed CD1d+ cell lines and primary leukemia cells." (PMID 22174854, 2011). "The expression of CD1d has been detected on some types of primary human leukemia blasts and on glioma cells." (PMID 20072624, 2010). "The leukemia cells we tested had negligible expression of CD1d." (PMID 40898981, 2026). "To investigate the cytolytic activity of 8F4CAR-iNK T cells mediated by the 8F4CAR and the iNK-TCR, we co-cultured the effector iNK T cells with PR1/HLA-A2+ or αGalCer/CD1d+ leukemia cell lines, and PR1/HLA-A2+ primary AML patient samples, then assessed the specific killing of target cells." (PMID 40519924, 2025). "However, the presence of CD1d on tumour cells is not a requirement, as iNKT cells can recognise leukaemia cells in a CD1d-independent manner and degranulate releasing Th1 cytokines towards the CD1d- leukaemia." (PMID 37153585, 2023). "A study on two leukemia cell lines-Jurkat cells (T lymphocytes) and K562 (myelogenous leukemia cell line) has unveiled the underlying mechanism of interaction in which LEF1 specifically binds to the CD1D promoter and regulates CD1D expression." (PMID 31684152, 2019). "Consequently, we assumed that CD1d expression on target cells is required to induce efficient leukemia cell lysis through DLI-iNKTs." (PMID 31354710, 2019). "In line with our previous findings, blockade of CD1d significantly reduced leukemia cell lysis." (PMID 31354710, 2019). "Interestingly, in certain patients with leukemia, higher CD1d levels have been detected on malignant cells that correlated with poorer prognosis and lower iNKT cell numbers." (PMID 29109728, 2017). "We observed that recipient mice transplanted with CD1d−/− TCL1 tumors died earlier from leukemia than mice transplanted with TCL1 tumors (CD1d−/− TCL1 n = 4; TCL1 n = 8; Log-rank Mantel Cox test p = 0.0009; Hazard Ratio 61.87; 95% Confidence Interval = 5.405 to 708.2)." (PMID 27385215, 2016).
leukemia (continued). "Interestingly, at 12 weeks of age before leukemia onset in CLL-prone mouse strains, dnRAG1, Eμ-TCL1, and DTG mice all showed significantly fewer transitional B cells in the CD1d-deficient strain background compared to their CD1d-proficient counterparts." (PMID 26537916, 2015). "In addition, Vδ3+ γδ T cells found in the liver of patients with leukemia or chronic viral infection recognized CD1d molecules and killed CD1d+ cells." (PMID 26284062, 2015). "However, direct cytotoxicity of human iNKT cells has been well demonstrated, especially against CD1d-expressing leukemia in vitro and in vivo." (PMID 23242316, 2013). "Therefore, we were interested in determining the expression of CD1d on leukemia cell lines." (PMID 31354710, 2019). "Therefore, higher expression of CD1d on leukemia cells could be an indicator of improved leukemia cell lysis and a prognostic factor for successful DLI-iNKT cytotherapy." (PMID 31354710, 2019). "In vitro studies using both leukemia cell lines and primary human AML blasts has demonstrated direct killing of leukemia cells in a CD1d-dependent manner by iNKT cells, an intriguing finding that warrants further mechanistic investigation." (PMID 38558819, 2024). "We first showed conclusively that CD1d+ tumor/Gal in hematological malignancy models, including a lymphoma (EL4), leukemia (WEHI3B), and plasmacytoma (J558) model, can induce antigen-specific CD4+ and CD8+ T cell immunity." (PMID 32231116, 2020). "Such DLI-iNKTs efficiently lysed leukemia cell lines and primary patient AML blasts ex vivo in a dose- and CD1d-dependent manner." (PMID 31354710, 2019). "We and others showed that NKT cells can show cytotoxicity against α-GalCer-loaded CD1d-expressing target cells, such as B16 melanoma, EL4 lymphoma, WHEI3B leukemia and NIH3T3 fibroblasts." (PMID 26121617, 2015). "We recently reported that iNKT cells recognize CD1d-negative leukemia cell line K562 in a TCR-dependent manner." (PMID 38319156, 2024). "Seven days after immobilized α-GalCer/CD1d-tetramer restimulation, iNKT cells exhibited cytotoxicity against autologous leukemic cells and produced IFN-γ, TNF-α, IL-2, and IL-4 upon stimulation with α-GalCer-pulsed leukemia cells." (PMID 32231116, 2020). "Almost all of the lymphocytes expressed the CD19+CD5+ leukaemia phenotype and 0% and 10.1% were positive for CD1d (data not shown)." (PMID 22174854, 2011).